OGT (O-linked N-acetylglucosamine (GlcNAc) transferase)
Diseases named in the same sentence as OGT in open-access papers (continued):
Sharing a sentence is not in itself a finding about the gene and the disease.
liver diseases (5 papers, 2023 to 2024). "The involvement of OGT in liver diseases is associated with many molecules and signaling pathways, but knowledge of its regulation in liver diseases is still limited." (PMID 38786029, 2024). "Conversely, decreased OGT is also linked with liver disorders." (PMID 36768465, 2023). "However, the precise role of high OGT expression in liver diseases associated with HCV infection remains unclear." (PMID 38827513, 2024). "More research is needed to further understand the functional implications of O‐GlcNAc modifications and the specific impact of elevated OGT expression in HCV‐related liver diseases." (PMID 38827513, 2024). "OGT-mediated O-GlcNAcylation contributes to the development of liver diseases by regulating various molecular signaling pathways." (PMID 38786029, 2024). "Interesting, we do see a discrepancy between the relationship between OGT and O-GlcNAcylation in human liver disease progression." (PMID 37930118, 2023). "This indicates that OGT might contribute to the advancement of HCV‐related liver disease through these particular mechanisms." (PMID 38827513, 2024). "Notably, the upregulation of OGT in HCV‐induced liver disease and cancer seems to be predominantly influenced by inflammation and fibrosis rather than being directly induced by HCV infection itself." (PMID 38827513, 2024). "Consequently, aberrant expression and function of OGT and OGA leads to changes in O-GlcNAcylation beyond this range, resulting in hepatocyte dysfunction and increased susceptibility to liver disorders." (PMID 36768465, 2023). "However, given the fact that OGT expression increases in a patient’s liver tissue during the development and progression of liver diseases, OGT may play a dual role in HCV morphogenesis." (PMID 38786029, 2024). "Under normal conditions, the expression of OGT is not high in the liver, while overexpressed OGT leads to pathological changes and hepatic disorders." (PMID 36768465, 2023).
osteosarcoma (5 papers, 2022 to 2024). A usually aggressive malignant bone-forming mesenchymal neoplasm, predominantly affecting adolescents and young adults. "Transwell assays were conducted to determine the effect of OGT on osteosarcoma cell migration and invasion." (PMID 38217543, 2024). "ARG-based gene signatures reliably predicted RFS and OS in osteosarcoma, and OGT showed promise as a potential biomarker." (PMID 38217543, 2024). "In osteosarcoma, pharmacological and genetic inhibitions of OGT lead to a reduction in DNA double-strand break repair mediated by RAD52-dependent homology recombination, ultimately resulting in cell cycle arrest and reduced cell proliferation." (PMID 37838167, 2023). "Our study shows that EBLN3P promotes the metastasis and drug resistance of osteosarcoma through miR-200a-3p/OGT axis." (PMID 36544170, 2022). "A domestic study in China reported the expression of OGT in osteosarcoma tissues increased and downregulating its expression increased the sensitivity of osteosarcoma cells to cisplatin." (PMID 36544170, 2022). "LncEBLN3P is upregulated in osteosarcoma and increases the MTX resistance in osteosarcoma cells through downregulating miR-200a-3p, which in turn promoted the EMT process of osteosarcoma cells by increasing the OGT." (PMID 36544170, 2022). "In vivo investigation and deeper clinical research are necessary to explore how does LncEBLN3P/miR-200a-3p/OGT axis regulate the MTX sensitivity in osteosarcoma." (PMID 36544170, 2022). "OGT may serve as a novel target to develop new therapeutic approaches and enhance the prognoses of osteosarcoma patients." (PMID 38217543, 2024). "Although O-linked N-acetylglucosamine transferase (OGT) has been identified as an ARG associated with patient prognosis, its functions in osteosarcoma remain unclear." (PMID 38217543, 2024). "Nevertheless, OGT has the potential to serve as an osteosarcoma prognostic biomarker." (PMID 38217543, 2024). "The mechanism of the oncogenic effect of OGT in osteosarcoma remains to be further verified." (PMID 38217543, 2024). "The mRNA level of OGT was high in multiple osteosarcoma cell lines." (PMID 38217543, 2024). "RT-PCR was used to measure OGT mRNA expression in various osteosarcoma cell lines." (PMID 38217543, 2024). "We showed that OGT knockdown inhibited osteosarcoma cell invasion and migration in vitro." (PMID 38217543, 2024). "Inhibition of OGT in osteosarcoma led to increased sensitivity to ferroptosis." (PMID 37838167, 2023). "Blocking OGT by OGT-si crippled the resistant effect of EBLN3P on MTX in osteosarcoma cells." (PMID 36544170, 2022). "Furthermore, upregulation of OGT almost counteracts the sensitization effect of miR-200a-3p to MTX in osteosarcoma cells." (PMID 36544170, 2022). "In summary, OGT promoted osteosarcoma metastasis and might be a prognostic biomarker." (PMID 38217543, 2024). "Therefore, OGT’s effects on osteosarcoma cells were investigated in vitro." (PMID 38217543, 2024). "Moreover, our study also showed that decreasing the expression of OGT in osteosarcoma cells could significantly enhance the sensitivity of osteosarcoma cells to MTX." (PMID 36544170, 2022). "Recently, a clinical study examined O-GlcNAcylation, OGT, and OGA expression in bone specimens derived from 109 patients diagnosed with osteosarcoma." (PMID 38915778, 2024). "Our study showed that miR-200a-3p was downregulated in osteosarcoma, resulting in the downregulation of downstream target gene OGT, which in turn promoted the EMT process of osteosarcoma cells, leading to the metastasis and MTX resistance of osteosarcoma cell." (PMID 36544170, 2022). "The decreased miR-200a-3p resulted in the upregulation of its target gene O-GlcNAc transferase (OGT), which in turn promoted the EMT process of osteosarcoma cells." (PMID 36544170, 2022).
osteosarcoma (continued). "We constructed an HBP-related gene signature containing five key genes (GPI, PGM3, UAP1, OGT, MGEA5) which showed a remarkable prognostic value for predicting prognosis and can guide immunotherapy and targeted therapy for osteosarcoma." (PMID 36275679, 2022). "Four ARGs-BRMS, COL4A2, FGF2, and OGT-were used to develop an RFS-predicting model, whereas seven ARGs-CD24, FASN, MMP2, EIF2AK3, ID2, PPARG, and PIK3R3-were used to develop an OS-predicting model in patients with osteosarcoma." (PMID 38217543, 2024). "We observed a negative relationship between miR-200a-3p and OGT expression levels in osteosarcoma tissues." (PMID 36544170, 2022). "Moreover, miR-200a-3p could not increase the sensitivity of MTX in osteosarcoma cells after OGT was overexpressed." (PMID 36544170, 2022).
colitis (4 papers, 2018 to 2023). Inflammation of the colon. "Paneth cell‐specific deletion of OGT led to Paneth cell dysfunction, which might predispose mice to chemical‐induced colitis." (PMID 29941542, 2018). "Meanwhile, in vivo studies have suggested the promotion of O-GlcNAcylation (such as OGT-transgenic mice) as an effective treatment in mice colitis." (PMID 34399822, 2021). "Mice with OGT deficiency either in IEC or Treg cells exhibited severe intestinal inflammation, indicating that OGT-modulated and Foxp3-based O-GlcNAcylation can regulate the development of colitis." (PMID 32369982, 2020). "Second, we did not experimentally verify the potential effects of hesperidin, coptisine and ginsenoside Rb1 on OGT and OGA activities in the colitis model." (PMID 34399822, 2021). "Immunohistochemistry staining indicated that OGT level was significantly reduced while OGA was obviously elevated in model group, which confirmed that colitis leads to a reduction in colonic O-GlcNAcylation level." (PMID 34399822, 2021). "Our results demonstrated that WMW can enhance OGT activity and suppress OGA activity, thereby increasing RIPK3 O-GlcNAcylation, and then inhibiting necroptosis, eventually alleviating TNBS-induced colitis." (PMID 34399822, 2021). "In this study, we demonstrated that the classic Chinese herbal formula WMW can alleviates TNBS-induced mice colitis, and the mechanisms involved may be as followed: WMW treatment can regulate colonic OGT and OGA activities, that is, enhance OGT activity and suppress OGA activity." (PMID 34399822, 2021).
dilated cardiomyopathy (4 papers, 2020 to 2025). Cardiomyopathy which is characterized by dilation and contractile dysfunction of the left and right ventricles. "Our findings show for the first time that ISRIB has protective effects in the context dilated cardiomyopathy due to OGT deficiency." (PMID 41101503, 2025). "Embryonic cardiospecific deletion of OGT has been shown to induce dilated cardiomyopathy and multiple cardiac defects, associated with changes of the transcriptome." (PMID 38737268, 2024). "Collectively, those data suggested that OGT was essential for heart development, with loss of OGT in early cardiomyocytes leading to dilated cardiomyopathy with multiple cardiac defects." (PMID 32251422, 2020). "Cardiomyocyte-specific overexpression of OGT led to increase in O-GlcNAc levels, contributing to dilated cardiomyopathy, ventricular arrhythmias and premature death." (PMID 40458788, 2025). "Interestingly the overexpression of cardiac OGT in transgenic mice also showed to have adverse effects leading to sever dilated cardiomyopathy by increasing O-GlcNAc levels, effects that were counteracted with an overexpression of OGA." (PMID 38737268, 2024).
endometrial cancer (4 papers, 2013 to 2021). Primary or metastatic malignant neoplasm involving the endometrium (mucous membrane that lines the endometrial cavity). "Analysis of gene expressions in cancer tissue samples from endometrial cancer patients confirmed the association between OGT or TET3 and EMT genes." (PMID 34948036, 2021). "In this study, we analyzed the impact of TET3 and OGT on migration and invasion of endometrial cancer cells via regulation of EMT genes expression." (PMID 34948036, 2021). "Our results contribute to the knowledge of the role of the TET3/OGT relationship in the complex mechanism supporting endometrial cancer progression." (PMID 34948036, 2021). "Our results show that both TET3 and OGT affect cell migration and invasion of endometrial cancer cells; however, unexpectedly, their effects are different in HEC-1A and Ishikawa cells." (PMID 34948036, 2021). "Here, we demonstrate that OGT and TET3 affect the expression of genes associated with epithelial-mesenchymal transition via changes of histones modifications and the ability of endometrial cancer cells for migration and invasion." (PMID 34948036, 2021). "Wound healing and Boyden chamber assays were conducted to evaluate the migration and invasion capacity of endometrial cancer cells with overexpression of OGT and TET3." (PMID 34948036, 2021). "Regarding the endometrial carcinomas, it appeared that OGT and OGA mRNA were significantly more elevated in grades II and III tumors than in grade I. In addition, OGT and OGA expression was higher in case of cancers with deep myometrial invasion." (PMID 23964270, 2013). "To further investigate whether OGT and TET3 were associated with the expression of EMT genes in endometrial cancer, we analyzed the correlations between these gene expressions in 131 samples of endometrial cancer tissues using quantitative PCR." (PMID 34948036, 2021). "Here, we demonstrated that in endometrial cancer cells both TET3 and OGT affected the expression of genes involved in epithelial to mesenchymal transition (EMT), i.e., FOXC1, TWIST1, and ZEB1." (PMID 34948036, 2021). "The impact of changes in OGT and TET3 amounts on the expression of genes involved in epithelial-mesenchymal transition (FOXA1, FOXC1, TWIST, ZEB1) in endometrial cancer cells has been analyzed." (PMID 34948036, 2021). "In conclusion, our results showed that both TET3 and OGT are involved in the regulation of FOXC1, TWIST1, and ZEB1 in endometrial cancer and affect cancer cell migration and invasion." (PMID 34948036, 2021).
esophageal squamous cell carcinoma (4 papers, 2012 to 2022). Esophageal squamous cell carcinoma (ESCC) is a type of esophageal carcinoma (EC) that can affect any part of the esophagus, but is usually located in the upper or middle third. "The aim of this present study was to explore the expression and clinical significance of O-linked N-acetylglucosamine (O-GlcNAc) transferase (OGT) and enzymatic O-linked glycosylation (O-GlcNAcation) through the addition of O-linked-β-N-acetylglucosamine in esophageal squamous cell carcinoma." (PMID 23554759, 2012). "RL2 antibody level was positively correlated with OGT expression, and the metastasis of lymph node, which means the level of O-GlcNAcation was high and related to the metastasis of lymph node in esophageal squamous cell carcinoma." (PMID 23554759, 2012). "OGT expression and O-GlcNAcation in 40 samples from patients with esophageal squamous cell carcinoma was detected by immunohistochemical staining with anti-OGT antib ody and O-GlcNAc-specific antibody RL2, respectively." (PMID 23554759, 2012). "The levels of OGT and O-GlcNAcation in esophageal squamous cell carcinoma and normal esophageal mucosa were detected by immunohistochemistry using anti-OGT antibody and RL2 antibody, respectively." (PMID 23554759, 2012). "In conclusion, OGT activation is the main reason for promoting the level of O-GlcNAcation in esophageal squamous cell carcinoma." (PMID 23554759, 2012). "The results indicated that OGT promoted O-GlcNAcation and played a more important role than OGA in esophageal squamous cell carcinoma, suggesting that in esophageal squamous cell carcinoma, OGT was the main protein responsible for O-GlcNAcation." (PMID 23554759, 2012). "Most normal esophageal tissues (30/35, 85.7%) showed low expression of OGT while esophageal squamous cell carcinoma tissues mostly (35/45, 77.8%) exhibited high expression (P < 0.01)." (PMID 23554759, 2012). "Our statistical analysis showed that OGT was highly expressed in esophageal squamous cell carcinoma, and was positively correlated with O-GlcNAcation (r = 0.996, P = 0.028)." (PMID 23554759, 2012). "Our study showed that OGT expression and O-GlcNAcation level were both increased in esophageal squamous cell carcinoma tissues compared to normal esophageal mucosa tissues (P < 0.05)." (PMID 23554759, 2012). "We found that the expression of OGT was higher in esophageal squamous cell carcinoma samples compared to the normal tissues." (PMID 23554759, 2012). "Decreasing O-GlcNAcation by inhibiting OGT may benefit treatment of esophageal squamous cell carcinoma." (PMID 23554759, 2012). "In this present study, we explored the expression of O-GlcNAc transferase (OGT) and O-GlcNAcation by immunohistochemistry using an O-GlcNAc-specific antibody-RL2 in esophageal squamous cell carcinoma." (PMID 23554759, 2012). "We found that the levels of both OGT and RL2 were high in esophageal squamous cell carcinoma, suggesting that O-GlcNAcylation may play an important role in esophageal squamous cell carcinoma." (PMID 23554759, 2012).
Hypoglycemia (4 papers, 2021 to 2024). A decreased concentration of glucose in the blood. "The VMH has been shown to initiate counterregulatory response to glucopenia or hypoglycemia, and we have shown that OGT expression in the VMH was increased after fasting." (PMID 36044565, 2022). "OGT is highly expressed in pancreatic glucagon-secreting cells (α-cells), which secrete glucagon in response to hypoglycemia." (PMID 33460647, 2021). "We hypothesize that OGT plays a key role in the maintenance of α-cell mass and proper function of secreting glucagon in response to hypoglycemia." (PMID 33460647, 2021).
microcephaly (4 papers, 2020 to 2026). A congenital or acquired developmental disorder in which the circumference of the head is smaller than normal for the person's age and sex. "Due to the plethora of processes regulated by O-GlcNAcylation, it is unclear which O-GlcNAc-dependent processes are dysregulated to cause microcephaly in OGT-CDG." (PMID 40592469, 2025). "Although Ogt has been shown to be important in all these processes, the mechanisms underlying microcephaly in OGT-CDG remain to be investigated." (PMID 38566589, 2024). "Loss of OGT catalytic activity leads to impaired O-GlcNAcylation homeostasis in the brain, changes in body size and mass, and microcephaly in OGTC921Y mice." (PMID 38566589, 2024). "Three probands with different OGT variants present with microcephaly, while megacisterna magna was found in two patients." (PMID 32080367, 2020). "Pathogenic variants in OGT are mainly associated with intellectual and developmental disability, microcephaly, eye abormalities, and coarse facial features with high, broad forehead, and triangular face." (PMID 32080367, 2020). "OGT-CDG is clinically heterogeneous, with different missense variants presenting with variable peripheral dysmorphias, muscle hypotonia, and neuroanatomical abnormalities including microcephaly." (PMID 40592469, 2025). "With a recently reported mouse model of a catalytically deficient OGT-CDG variant, future work investigating the possible mechanistic link between DDX3X O-GlcNAcylation and microcephaly may yield insights into the aetiology of this poorly understood disease." (PMID 40592469, 2025). "Our results here suggest that hypo-O-GlcNAcylation of DDX3X could be a candidate conveyor of the microcephaly observed in OGT-CDG patients." (PMID 40592469, 2025). "As OGA has been implicated in intelligence, and because Oga knockdown leads to microcephaly and hypotonia in mice, loss of OGA might also contribute to the OGT-CDG phenotype." (PMID 38566589, 2024).
non-alcoholic fatty liver disease (4 papers, 2022 to 2025). "The elevated O-GlcNAcylation and OGT expression have been involved in facilitating tumor growth and metastasis in HCC, and the repression of OGT may be a promising treatment modality for nonalcoholic fatty liver disease." (PMID 37559097, 2023). "Moreover, an increase in FAS-dependent PA accumulation in non-alcoholic fatty liver disease (NAFLD) liver cancer cells was attributed to higher OGT levels." (PMID 36111295, 2022). "Another study showed that bisphenol A (BPA) enhances OGT-mediated O-GlcNAcylation of NLRP3, leads to abnormal lipid accumulation, and induces pyroptosis in HepG2 cells, thus accelerating the progression of non-alcoholic fatty liver disease (NAFLD) in vitro." (PMID 41059334, 2025). "In parallel, another study explored the impact of OGT-mediated O-GlcNAcylation induced by bisphenol A on NLRP3 stability and cell pyroptosis in non-alcoholic fatty liver disease (NAFLD)." (PMID 39742284, 2024).
prostate adenocarcinoma (4 papers, 2022 to 2024). "Collectively, we proposed that KIF1A facilitated NE transdifferentiation of prostatic adenocarcinoma via modulation of OGT and O-GlcNAcylation of OCT4 and β-catenin." (PMID 39505875, 2024).
renal cell carcinoma (4 papers, 2022 to 2025). "Knocking down OGT has been shown to increase sensitivity to sunitinib in renal cell carcinoma (RCC)." (PMID 41059334, 2025). "Together, these data indicate that OGT-mediated O-GlcNAcylation of UBAP2L at serine 305 regulates stress granule formation and sunitinib resistance in renal cell carcinoma." (PMID 41029457, 2025).
asthma (3 papers, 2019 to 2025). "The epithelial alarmin TSLP induces the expression of CUL5, which then interacts with and degrades OGT via K48-linked ubiquitination, inhibiting MAVS O-GlcNAcylation and IFN-β production, and eventually inducing asthma exacerbations." (PMID 38177117, 2024). "Given the role of OGT-mediated MAVS O-GlcNAcylation in the CUL5-mediated inhibition of antiviral immunity in vitro, we investigated the role of OGT in CUL5-mediated asthma exacerbations in vivo." (PMID 38177117, 2024).